PINK1 (PTEN induced kinase 1)
Diseases named in the same sentence as PINK1 in open-access papers (continued):
Sharing a sentence is not in itself a finding about the gene and the disease.
Anxiety (14 papers, 2017 to 2026). Intense feelings of nervousness, tension, or panic often arise in response to interpersonal stresses. "Pink1 deficiency can enhance neurological deficits, brain edema, and anxiety-like behavior after ICH." (PMID 38266580, 2024). "Studies in Pink1 deficient mice have also identified links between dysregulation of mitophagy, cellular stress responses and anxiety and several studies in Pink1–/–rats have identified gene impacts on behavioral measures of anxiety in open field, light/dark box and elevated plus maze testing." (PMID 40963536, 2025). "Finally, and most directly relevant to PD are findings showing that among patients with monogenic forms of illness, those in whom disease is related to PINK1 mutations are at elevated risk for neuropsychiatric symptoms, including anxiety." (PMID 40963536, 2025). "All of these data indicated that Pink1 deficiency could promote the anxiety of mice caused by ICH." (PMID 38266580, 2024). "These and other signs of an anxiety remained through final testing of the female Pink1–/– cohort at 12 months of age." (PMID 40963536, 2025). "Data from this study suggested that the phenotype of elevated anxiety in male Pink1–/– rats is transient." (PMID 40963536, 2025). "The present study used EPM testing to further explore questions about the development of behavioral indices of anxiety in male and female Pink1–/– rats." (PMID 40963536, 2025). "Specifically, at this age female Pink1–/– rats made markedly fewer entries and spent noticeably less time in open arms compared to WT females –both of which are behavioral measures suggesting increased anxiety in the Pink1–/– group relative to controls." (PMID 40963536, 2025). "The Red module, which contained the Pink1 gene, correlated to open field number of entries (movement into the open field indicating less anxiety; increased exploration)." (PMID 38438964, 2024). "The Pink1−/− rat was selected because it exhibits parallels to human prodromal PD features, including early and progressive changes to vocalization and anxiety with a gradual onset of limb motor dysfunction in adults." (PMID 38438964, 2024). "We also found that PINK1−/− rats spent on average a higher percentage of the 1 h OFT time in the center of the arena compared to WT rats, suggesting a lower level of anxiety (WT mean: 19.51, sd: 8.49; PINK1−/− mean: 29.44, sd: 13.88)." (PMID 38817910, 2024). "Specifically, female Pink1−/− rats demonstrate less anxiety-like behavior compared to male Pink1−/− rats and female rats show increased locomotor activity compared to male rats." (PMID 36172466, 2022). "Mixed sex groups of Pink1−/− rats and wildtype (WT) controls were assayed for limb motor, anxiety, and vocal motor behaviors." (PMID 36172466, 2022). "Taken together, this data suggests that Pink1−/− rats have increased anxiety-like behavior and female rats have decreased anxiety-like behavior at 2 months of age." (PMID 36172466, 2022). "Pink1−/− rats, a rodent model of PD mitochondrial dysfunction, exhibit early stage behavioral deficits, including vocal communication and anxiety, that progress during mid-to-late adulthood (6–12 months of age)." (PMID 36172466, 2022). "Previous Pink1−/− rat studies used light-dark box and/or elevated plus maze to track anxiety-like behaviors over time." (PMID 36172466, 2022). "Previous rodent studies suggest that male and female Pink1−/− rats demonstrate an increase in anxiety-like behavior compared to WT controls." (PMID 36172466, 2022). "Thus, in testing at 3 and 5 months of age multiple measures of behavior indicated that levels of anxiety in the Pink1–/– females were significantly lower than those of WT female controls." (PMID 40963536, 2025). "Thus, behavioral indices of heightened anxiety were expected to emerge in early adulthood to greater to exclusive extents in female compared to male Pink1 rats, and to progressively worsen over time." (PMID 40963536, 2025).
Anxiety (continued). "Thus, outcomes from both paradigms suggest that anxiety levels are reduced in young adult female Pink1–/– rats relative to WT female controls." (PMID 40963536, 2025). "These indices of relative open arm avoidance data suggested elevated anxiety in male Pink1–/– rats." (PMID 40963536, 2025). "The studies presented here tested the hypothesis that Pink1–/– rats more aptly recapitulate core clinical characteristics of anxiety disturbances in PD, including their early premotor/prodromal onset and increased prevalence and severity in females." (PMID 40963536, 2025). "However, in EPM testing at 8 months old, indices of anxiety in Pink1–/– females changed dramatically." (PMID 40963536, 2025). "Particularly relevant to the present studies are findings that patients with PINK1-related forms of PD are also at elevated risk for non-motor deficits impacting cognition and neuropsychiatric domains including anxiety." (PMID 40963536, 2025). "However, in testing at 7, 9 and 12 months of age, a very different set of behaviors emerged that suggested that anxiety levels had become significantly higher in Pink1–/– compared to WT female controls." (PMID 40963536, 2025). "The studies presented explored whether rats with knockout of PTEN-induced putative kinase 1 gene (Pink1–/–) might serve as sex-specific preclinical models of anxiety in PD that are suitable to fill this gap." (PMID 40963536, 2025). "This bias toward closed, relatively protected parts of the maze complements open arm findings from the prior study could indicate a phasic elevation in anxiety in male Pink1–/– rats at around this age." (PMID 40963536, 2025). "Another goal of this study was to use bioinformatics to highlight biological gene pathways within the whole blood and determine whether they are significantly correlated to anxiety, motor, or ultrasonic vocalization behavioral outcomes in Pink1−/− rats." (PMID 38438964, 2024). "In addition, Pink1–/– rats also show behavioral correlates reflecting increased anxiety, e.g., changes in distress vocalizations, social approach, open vs. closed arm entries in elevated plus maze testing." (PMID 36560930, 2022). "Additionally, female Pink1−/− rats demonstrate significantly less anxiety-like behavior compared to male Pink1−/− rats." (PMID 36172466, 2022). "Additionally, studies have shown that the Pink1−/− rat shows anxiety-like behavior between 8 and 12 months and early anhedonia at 2 months; these signs are analogous to early clinical manifestations in humans." (PMID 36172466, 2022). "Previous observations in Pink1–/– rats include behavioral measures suggesting increased anxiety." (PMID 36560930, 2022). "While previous bodies of work have assessed locomotor and vocal motor behavior in this model as longitudinal studies, this study is the first to explore the differences in locomotion, anxiety, and vocalization between Pink1−/− male and female rats as young adults (2 months of age)." (PMID 36172466, 2022). "This study reports differences in limb sensorimotor function, cranial motor ultrasonic vocalization behavior, and anxiety as well as gene expression transcript levels in the brainstem and vocal fold (TA) muscle between male and female Pink1−/− rats at 2 months of age." (PMID 36172466, 2022). "Thus, the present studies not only add to a growing consensus for Pink1–/– rats as modeling anxiety disturbances in PD, they also affirm the relatively unique features of this strain in modeling the sex differences that distinguish symptoms of anxiety in PD." (PMID 40963536, 2025). "However, inconsistencies across studies have left it unclear whether and to what extent Pink1–/– rats aptly recapitulate the female over male differences in PD-related disturbances in anxiety that are observed clinically." (PMID 40963536, 2025).
Anxiety (continued). "However, by 7 months of age, behaviors in female Pink1–/– rats–and only the females, evolved into ones that continue to show signs of hyperactivity but that also reflect significantly heightened anxiety, e.g., avoidance of open arms and especially their distal ends." (PMID 40963536, 2025). "Thus, it is perhaps not surprising that evidence for anxiety phenotypes in Pink1 deficient and Pink1–/– rats and mice continues to grow." (PMID 40963536, 2025). "Additionally, the PINK1−/− rats did not exhibit any other prototypical behaviors associated with anxiety, thereby ruling out anxiety as a confound." (PMID 38817910, 2024). "Thus, interpretations with respect to decreased grooming in the Pink1–/– group leave it uncertain as to whether this difference reflects decreased or increased anxiety." (PMID 36560930, 2022). "Based in part on recent evidence showing that Pink1–/– rats model the increased vulnerability of male PD patients for non-motor deficits in cognition and memory, it was hypothesized that this strain would also recapitulate the greater vulnerability of female PD patients to anxiety disturbances." (PMID 40963536, 2025). "Behavioral analyses revealed that mice with Pink1 knockdown, upon ART treatment, exhibited intensified anxiety, depressive behavior, and social disturbances in the PTM + PBS + sh-vector group compared to the sham + PBS + sh-vector group." (PMID 38745240, 2024). "Overall, male Pink1–/– rats exhibited greater activity, little to no indications of increased anxiety and less habituation to repeated testing than sex-matched controls." (PMID 40963536, 2025). "These increased/increasing signs of anxiety were in sharp contrast to behaviors in WT females that explored the open spaces of the maze more and more over time, and clearly demonstrate the development of an anxiety phenotype in Pink1–/– females that is largely absent in male Pink1–/– rats." (PMID 40963536, 2025). "Thus, while similar to Pink1–/– males in showing hyperlocomotion, the young adult Pink1–/– female rats displayed multiple behaviors suggesting anxiety relative to WT controls rather than unchanged behavioral indicated of anxiety observed in Pink1–/– males." (PMID 40963536, 2025).
Huntington disease (14 papers, 2012 to 2026). Huntington disease (HD) is a rare neurodegenerative disorder of the central nervous system characterized by unwanted choreatic movements, behavioral and psychiatric disturbances and dementia. "Studies have shown that Pink1 overexpression is beneficial for certain neurodegenerative models, such as Huntington’s Disease and α-synuclein model in Drosophila." (PMID 31714929, 2019).
Obesity (14 papers, 2021 to 2026). Accumulation of substantial excess body fat. "Research has reported that the transcription level of PINK1 is negatively correlated with the risk of diabetes in obesity." (PMID 37920803, 2023). "Loss of NLRP3 reverses BAT dysfunction and obesity in PINK1 KO mice." (PMID 37582956, 2023). "Enhancing H19 expression suppresses excessive mitophagy by restricting the translation of Pink1 mRNA, thereby alleviating obesity-induced cardiomyopathy." (PMID 40004130, 2025). "Our findings reinforce these observations, suggesting that the PINK1/Parkin axis is upregulated as a compensatory mechanism in human obesity and BNIP3L protein expression is increased in adipocytes." (PMID 41334630, 2025). "In ob/ob mouse hearts, the long non-coding RNA H19 has been shown to inhibit excessive PINK1/Parkin-dependent mitophagy by restricting the translation of Pink1 mRNA, thereby ameliorating obesity-related cardiomyopathy." (PMID 40004130, 2025). "H19 inhibits excessive mitophagy by limiting Pink1 mRNA translation, thus alleviating this cardiac defect that occurs during obesity." (PMID 34050133, 2021). "In the present study, we concluded that H19-mediated Pink1 regulation is critically involved in obesity-induced mitochondrial suppression and cardiac dysfunction." (PMID 34050133, 2021). "Similarly, PINK1 gene expression was notably higher in the group of obesity than in the controls, also demonstrating statistical significance (p = 0.01)." (PMID 41334630, 2025). "Comprehending the interplay between mitophagy, inflammation, and metabolic health in obesity requires functional studies, such as targeted knockdown of PINK1, PARK2, or BNIP3L in adipocytes, to elucidate their specific roles in regulating mitochondrial quality and inflammatory responses." (PMID 41334630, 2025). "Supplementation with thymol prevents excess liver fat accumulation in a mouse model of diet-induced obesity, improves pink-1-dependent heat stress resilience in Caenorhabditis elegans, and slows the decline of skeletal muscle performance while delaying epigenetic aging in SAMP8 mice." (PMID 40993327, 2025). "Also, Wang and colleagues found that Long non‐coding RNA H19 exerts a restraining effect on excessive mitophagy by restricting the expression of Pink1 protein, which alleviates this cardiac abnormality that arises during the condition of obesity." (PMID 37039609, 2023). "In mice, depletion of PINK1, the core regulator of mitophagy, in either the whole body or brown adipose tissue, resulted in brown adipose tissue dysfunction and a tendency towards obesity." (PMID 37920803, 2023). "To summarize, our study demonstrates a significant upregulation of mitophagy-related markers, including PINK1, PARK2, and BNIP3L, in the adipocytes of visceral adipose tissue in individuals with obesity." (PMID 41334630, 2025). "Our study demonstrated that the mitophagy-related markers PINK1, PARK2, and BNIP3L were significantly upregulated in the visceral adipose tissue of individuals with obesity." (PMID 41334630, 2025). "Moreover, the expression of PARK2, PINK1, and BNIP3L was significantly upregulated in the obesity group, suggesting increased mitophagy activity in adipose tissue." (PMID 41334630, 2025). "Collectively, these results showed that Pink1/Parkin signaling, but not Fundc1 or Bnip3/Nix, was crucial for enhanced mitophagy in the heart or H9c2 cells in metabolic disorders during obesity." (PMID 34050133, 2021). "Interestingly, palmitic acid (PA) induced increased expression of PINK1 and Parkin in podocytes, indicating that PINK1/Parkin-mediated mitophagy was activated in lipid-induced lipotoxicity, which was confirmed in the rat model of HFD-induced obesity." (PMID 33546409, 2021).
type 2 diabetes (14 papers, 2014 to 2025). "Given the link between glucose metabolism, mitochondrial function and insulin secretion in β-cells, and the reported association of PD with type 2 diabetes, we investigated the response of PINK1-deficient β-cells to glucose stimuli to determine whether loss of PINK1 affected their function." (PMID 24806840, 2014). "Metformin preserved mitochondrial health in the mononuclear cells of patients with type 2 diabetes by increasing the expression of the gene of mitophagy: PINK1, Parkin, LC3, and NIX." (PMID 39859520, 2025). "Here, we present evidence that Pink1–Park-mediated mitochondrial fragmentation affects the kidney filtration system and reduces renal function in a fly model of type 2 diabetes." (PMID 38602042, 2024). "This study explored the potential of saponins from Korean Red Ginseng to target the PINK1/Parkin mitophagy pathway, aiming to enhance insulin sensitivity in hepatocytes—a key factor in metabolic disorders like metabolic dysfunction-associated steatotic liver disease (MASLD) and type 2 diabetes." (PMID 38998642, 2024). "Pioglitazone, an anti-diabetic drug for Type 2 diabetes mellitus (T2DM) under the category of thiazolidinediones (TZDs), increases PINK1 expression via NF-κB activation and enhances mitophagy." (PMID 36257956, 2022). "Thus, it reverses the changes observed in PBMCs from type 2 diabetic patients, who are characterized by down-regulation of MFN2, PINK1, PARKIN, and LAMP-2 genes at the mRNA and protein level." (PMID 30356025, 2018).
cognitive decline (13 papers, 2019 to 2025). "Unsurprisingly, we found that CQ treatment caused a distinct cognitive decline in hTau and PINK1 overexpressing mice." (PMID 35059394, 2021). "For example, EOPD with PRKN, PINK1, or DJ-1 mutations are characterized by good response to L-dopa treatment, dystonia and dyskinesia being relatively common, cognitive decline relatively uncommon and a slower deterioration of the disease when compared with idiopathic PD." (PMID 36437996, 2022). "Premotor cognitive decline in human PD can potentially be examined in the genetically altered PINK1−/− rat model, which exhibits a protracted onset of motor decline in most studies." (PMID 38817910, 2024). "The relationships between the observed correlations of diet and the CSF1R, IGF1R, and PINK1 expression with regard to cognitive decline are less clear." (PMID 36771351, 2023). "Mice lacking PINK1 seem to develop Aβ plaques and mitochondrial abnormalities earlier, while PINK1 overexpression promotes the removal of damaged mitochondria and reduces synaptic defects and cognitive decline in mice." (PMID 36267702, 2022). "In conclusion, data regarding cognitive function in PINK1-PD is scarce, overall suggesting that cognitive decline is rare in this genetic form of PD." (PMID 35003622, 2021). "In this review, we summarize data regarding cognitive function on clinical studies, neuroimaging, and biological markers of cognitive decline in autosomal dominant PD linked to mutations in LRRK2 and SNCA, autosomal recessive PD linked to Parkin and PINK1, and also PD linked to GBA mutations." (PMID 35003622, 2021). "We also found that overexpression of PINK1 effectively reduced neuropathological accumulation of tau proteins, ameliorated mitochondrial function, attenuated damage to neurons and synapses, and thus rescued cognitive decline in hTau mice." (PMID 35059394, 2021). "To investigate whether changes in mitophagy reflect cognitive decline in FTLD individuals, we correlated the levels of mitophagy biomarkers (PINK1, ULK1, BNIP3L, TFEB) with global cognition (MMSE) and cognitive composite scores." (PMID 39972393, 2025).
Dystonia (13 papers, 2019 to 2025). An abnormally increased muscular tone that causes fixed abnormal postures. "The motor phenotype of DJ-1 is similar to that of PRKN and PINK1 mutation carriers, including dystonia and L-Dopa-induced dyskinesias." (PMID 40722695, 2025). "A case–control study reported painful episodes of torticollis and painful dystonia in a homozygous Q456X PINK1 pathogenic variant carrier." (PMID 38020640, 2023). "Painful episodes of torticollis and levodopa-induced painful dystonia episodes in 1 homozygous Q456X PINK1 mutation patient." (PMID 38020640, 2023). "These three patients all appear to have young onset PD, with prominent dystonia, resembling similar cases with PRKN and PINK1 mutations." (PMID 33770142, 2021). "However, PINK1 patients often show uncommon characteristics which can help differential diagnosis, including hyperreflexia, dystonia at onset, early L-dopa induced dyskinesias, and psychiatric and behavioral disturbances." (PMID 34831247, 2021). "Furthermore, patients with PINK1 mutations have a similar disease course as PRKN mutation carriers, with a good response to L-dopa treatment, but early dystonia and L-dopa induced dyskinesias." (PMID 34281267, 2021). "The current evidence for PRKN, PINK1 and DJ1 point to a sustained L-dopa response with lower doses, albeit with early motor complications that include dyskinesias and dystonia." (PMID 34281267, 2021).